STRAP (serine/threonine kinase receptor associated protein)
Diseases named in the same sentence as STRAP in open-access papers (continued):
Sharing a sentence is not in itself a finding about the gene and the disease.
cancer (19 papers, 2014 to 2025). A tumor composed of atypical neoplastic, often pleomorphic cells that invade other tissues. "It remains to be determined how different oncogenic signaling pathways regulated by STRAP are integrated together in different stages of cancer progression, depending on the genetic mutations." (PMID 40558481, 2025). "Deregulated expression of STRAP is associated with other human cancers, including those of the lung, colon, and breast." (PMID 28436936, 2017). "Since, STRAP expression is found to be high in most of the cancers, and NF-κB signaling is also directly linked to aggressive cancers; thus, STRAP-mediated NF-κB regulation may contribute to its oncogenic activity." (PMID 40558481, 2025). "Recent studies have shown that overexpression and misregulation of STRAP are associated with the development of multiple cancers and thus it could be considered a new therapeutic target for cancer." (PMID 33134183, 2020). "One such protein, STRAP, is found to be upregulated in most epithelial cancers and has been directly correlated with poor prognosis in cancer patients." (PMID 40558481, 2025). "Research has demonstrated that STRAP plays a role in the amount of cell growth and cancer progression pathways." (PMID 40558481, 2025). "STRAP-driven enhancement of β-Catenin signaling plays a crucial role in maintaining cancer stem cells, as demonstrated by the elevated expression of markers like LGR5 and AXIN2 in HCC cells." (PMID 40558481, 2025). "Altogether, STRAP inhibits TGFβ-mediated Smad signaling through TβR-I/TβR-II and/or Smad6/7 interactions and contributes towards the growth-promoting activities of cancer cells." (PMID 40558481, 2025). "STRAP regulates many pathways in human cancers, such as the Wnt/β-catenin pathway, MEK/ERK pathway, and TGF-β signaling." (PMID 38365721, 2024). "It has been suggested that lncRNA TRINGS protected cancer cells from death by inhibiting STRAP-GSK3β-NF-κB necrotic signaling." (PMID 37504305, 2023). "STRAP is a receptor-interacting protein that has an important role in cell proliferation, cell death and cancer development." (PMID 38003247, 2023). "Studies in various cancer cell lines also demonstrate that STRAP augments cell proliferation and oncogenesis by blocking the antiproliferative effects mediated by TGF-β signaling." (PMID 29849900, 2018). "STRAP overexpression increases levels of Notch target genes through transcriptional activation and maintains the cancer stem cell population (increased BMI1, CD24, CD44, EPCAM, CD29, and PSEN1), which may lead to enhanced chemoresistance." (PMID 40558481, 2025). "Therefore, the upregulation of STRAP induces cell proliferation and survival by impeding cell cycle arrest and apoptosis in normal and cancer cells, suggesting its prooncogenic activities." (PMID 40558481, 2025). "EWS overexpression in cancer has been directly correlated with STRAP upregulation." (PMID 40558481, 2025). "Furthermore, we demonstrated STRAP’s role in promoting cancer cell stemness as STRAP KO resulted in decreased mRNA abundance of stemness markers, CD133 expression, and tumorsphere formation." (PMID 34206917, 2021). "Supportive of this, the cancer genes HNRNPA1 and STRAP exhibit high expression in diverse cancers." (PMID 32634135, 2020). "Under the normal physiological conditions, STRAP promotes cell survival and proliferation and inhibits cell cycle arrest and apoptosis in normal and cancer cells, indicating that STRAP may function as an antiapoptotic protein." (PMID 29849900, 2018). "By contrast, changes in redox balance induce cell death by STRAP in normal and cancer cells, implying that STRAP may also function as a proapoptotic protein." (PMID 29849900, 2018). "We also review the dual roles of STRAP in cancer, which may contribute to the development of a novel therapeutic option for cancer treatment." (PMID 29849900, 2018).
cancer (continued). "Collectively, the findings of the present study reveal a positive regulatory role of STRAP in TLR signaling, which could provide additional insight into the potential prognostic and therapeutic implications of STRAP in various forms of cancer." (PMID 27934954, 2016). "Moreover, STRAP depletion enhanced the formation of SMN-positive Cajal bodies in cancer HeLa cells." (PMID 39337533, 2024). "Similarly, the protein STRAP promotes tumorigenicity and metastasis in various cancers." (PMID 32634135, 2020). "Further studies are needed to define the functions of STRAP and the redox-sensitive intracellular signaling pathways that enhance either cell proliferation or cell death in human cancer tissues, which may help in the development of effective treatments for cancer." (PMID 29849900, 2018). "Therefore, the upregulation of STRAP in solid tumors, coupled with its various pro-oncogenic functions and crosstalk with oncogenic signaling, provides a strong rationale for it to be a potentially important drug target for therapeutic intervention in human cancers." (PMID 40558481, 2025). "Among these, MLF2, COPS7A, PEX5, DDX47, STRAP and MRPL51 displayed strong correlations with USP5 in most cancer types." (PMID 37268697, 2023). "In particular STRAP, TRAP1, and PAK2 refer to TGF-β signaling, whose alteration contributes to many diseases, including cancer and fibrosis." (PMID 35051051, 2021). "In contrast, the cancer genes HNRNPA1, PPP2RC5, STRAP, DNAJC14, ATF1 showed upregulation in the cell subpopulations GSC and CD133pos./CD15pos. cells and are located in chromosomal regions that had gains in GSC and CD133pos./CD15pos. cells." (PMID 32634135, 2020). "The cancer genes HNRNPA1, PPP2RC5, STRAP, DNAJC14, and ATF1 showed upregulation in GSC and CD133pos./CD15pos. cells and were included in chromosomal regions that showed gains for GSCs and CD133pos./CD15pos.cells." (PMID 32634135, 2020). "Hence, further studies investigating the dual functions of STRAP, as well as its regulation by redox-dependent signaling, which induces either cell death or cell proliferation in human cancers, are needed because they may contribute to the development of more effective cancer treatments." (PMID 29849900, 2018). "Therefore, based on our findings, it is also possible that the aberrant expression or misregulation of STRAP might affect NF-κB activation, along with suppression of TGF-β signaling, thereby potentially contributing to the development of various cancers." (PMID 27934954, 2016).
STRAP also shares sentences with these, for which no sentence is quoted: cholangiocarcinoma (2 papers); gastric cancer (2); Hypertension (2); Alzheimer disease (1); cervical cancer (1); chronic kidney disease (1); colon adenocarcinoma (1); colorectal tumors (1); gastric tumor (1); Macrocephaly (1); neurological diseases (1); ovarian carcinoma (1); pancreatic ductal adenocarcinoma (1); seminoma (1); spinal muscular atrophy, type 1 (1); Thrombocytopenia (1); triple-A syndrome (1).